TWIST1 (twist family bHLH transcription factor 1)
Diseases named in the same sentence as TWIST1 in open-access papers (continued):
Sharing a sentence is not in itself a finding about the gene and the disease.
tumor (continued). "Furthermore, our results indicate that the Twist1-Jagged1-KLF4 axis plays an important and essential role in inducing tumor-derived endothelial differentiation inside the tumors in addition to traditional angiogenesis and in creating better opportunities for tumor metastasis." (PMID 26823670, 2016). "Twist1 and Twist2, as the main EMT-mediated process regulators, express high structural homology, and gene deletion tests have proved that two proteins share some similar effects and functions, such as their role in tumor progression and metastasis and their regulation of hematological malignancies." (PMID 26842802, 2016). "Notably, other important EMT-related markers such as SNAI1, SNAI2, ZEB1, ZEB2 and TWIST1 at the invasive tumor front were not thoroughly examined in these reported studies." (PMID 26214683, 2015). "For instance, immunohistochemical expression of TWIST1 and TWIST2, known activators of EMT, was significantly positively correlated with a tumor-budding phenotype (both low-grade and high-grade budding), yet their expression was virtually restricted to stromal cells in the tumor microenvironment." (PMID 25806371, 2015). "However, comparison of the tumor-adjacent gastric tissue between HP+ and HP- patients revealed 8 differentially methylated CpG sites located within 7 genes (CCNA1, CSPG2, DAB2IP, DIO3, FLT1, STAT5A and TWIST1)." (PMID 24674026, 2014). "Targeting the critical factors that contribute to the EMT process, such as Snail, Slug and Twist1, has beneficial effects for cisplatin-based therapies, further generalizing a model that correlates the degree of cisplatin sensitivity with the EMT status of tumour tissues." (PMID 23629957, 2013). "Furthermore, Twist1 did not alter the mechanism of tumor regression between CR OFF and CRT OFF lung tumors." (PMID 22654667, 2012). "Apparently, HIF-2α could regulate Twist1 in cells undergoing an EMT, and Bmi1 is essential for Twist1-induced EMT and tumor-initiating capacity, we found that HIF-2α regulates Bmi1 and Twist1 transcription by directly binding to their promoters under arsenite exposure." (PMID 22662215, 2012). "To gain insight into the role of EMT commitment in tumor initiation and primary tumor growth, we used a Twist1 transgenic mouse model exhibiting a lox-STOP-lox (LSL) version of the active version of the murine TWIST1 (TWIST1-E12 tethered dimer) under a ubiquitous promoter." (PMID 22654675, 2012). "Neither wild-type nor MMTV-Cre;Twist1 mice exhibited tumor formation by one year of age (n = 47)." (PMID 22654675, 2012). "In support of this hypothesis, PP2A, has recently been identified as a tumor suppressor and B56δ containing PP2A complexes could play a role in regulating Twist1 function in cancer via control of the phosphorylation state of Twist1." (PMID 18855684, 2008). "Additionally, TWIST1 was significantly downregulated in the VTT and showed borderline downregulation in the TC compared to N. TWIST1, a basic helix-loop-helix transcriptional factor expressed in various types of carcinomas, is a key player in tumour metastasis by inducing the EMT." (PMID 40869272, 2025). "Moreover, in tumor tissues from HCC patients treated with PPI, the density of VM structures (PAS+/CD31-) was markedly reduced, accompanied by the downregulation of VM-related markers (VE-cadherin, VEGFR1/2) and EMT markers (Twist1, Vimentin), as well as the upregulation of E-cadherin." (PMID 41019994, 2025). "However, we cannot rule out the possibility of endogenous Twist1 mRNA production by neurons, which may involve stimulation by tumor-derived EVs or potential stress induced by subcutaneous tumor growth." (PMID 40963917, 2025). "According to the role of TWIST1 in EMT, its significant decreased expression following MEIS1 silencing in KYSE‐30 cells may inhibit EMT progress and invasiveness behavior of the cells, and reverse the process of mesenchymal transition which may result in tumor cell differentiation." (PMID 31090196, 2019).
tumor (continued). "Interestingly, these two studies demonstrated that both Snail and Twist1 are transiently expressed and needed for initial EMT-mediated invasion and dissemination, but their corresponding expression should be shut down for metastatic outgrowth in each tumour context." (PMID 31091749, 2019). "Interestingly, TWIST1 expression may be epigenetically regulated as shown by hypermethylation of the promoter region in stromal areas containing low /absent numbers of tumor buds." (PMID 31316988, 2019). "Moreover, Twist1 and ZEB1 could promote CAF hyperproliferation by blocking cell cycle control through repression of cyclin‐dependent kinase inhibitors, as described for tumour cells." (PMID 28544627, 2017). "To further validate whether Twist1 could promote NPC radioresistance in vivo, we employed a xenograft mouse model, where we injected CNE2-EV and CNE2-T cells to nude mice, and found the tumor sizes of the CNE2-T group were larger than those in the CNE2-EV group." (PMID 27793033, 2016). "However, we still cannot determine whether the regulation of TWIST1 expression by FAM64A through STUB1-mediated TWIST1 ubiquitination is the specific mechanism and whether there are other molecular mechanisms by which FAM64A inhibits OC tumor progression, which still needs further investigation." (PMID 40424038, 2025). "Increased expression of tumor-promoting genes like VIM (vimentin) and TWIST1 (Twist Family BHLH Transcription Factor 1) vs. baseline was detected with 100 mg/d of aspirin but not with the other two higher doses." (PMID 38495101, 2024). "Given the diverse roles being played by TWIST1 and other EMT factors across multiple tumor types, it is no surprise that targeting EMT has gained interest as a therapeutic strategy." (PMID 38139368, 2023). "Finally, the tumor-suppressor miRNA let-7 inhibits EMT through binding to multiple target sites in the 3′UTR of high mobility group A2 (HMGA2), a chromatin-binding protein that could directly bind to the promoter regions of SNAIL and TWIST1 and promote their expression." (PMID 36114510, 2022). "Tumor cell proliferative index (phospho histone three expression) and apoptosis (cleaved caspase three) between MYC- and MYC/Twist1-HCC were not different." (PMID 31933479, 2020). "The deletion of Twist1 or Snai1 alone was not sufficient to suppress EMT, while the deletion of ZEB1 had a greater impact on the tumour phenotype and metastasis." (PMID 33207810, 2020). "Against this possibility, the tumor burden in the liver was not statistically different between MYC and MYC/Twist1 mice." (PMID 31933479, 2020). "TGFb/ID1 signals promote metastatic colonization via a MET, antagonizing TWIST1 EMT in normoxic metastatic sites, but not in hypoxic primary tumor sites, where EMT is governed by SNAIL1." (PMID 30899759, 2019). "In contrast to CXCL12 and TWIST1 methylation, the epigenetic regulation of the SNAI2 gene was previously determined only in BC cell line models, not in tumour samples." (PMID 30189837, 2018). "Expression of eight additional genes associated with EMT was initially analyzed individually; a good correlation between tumor sensitivity to BI 853520, and gene expression was observed for MUC13 and POF1B but not for TWIST1." (PMID 29472531, 2018). "Taking into the account the co-expression of TWIST1 and ZEB2, we found that patients with expression of both proteins had significantly poorer survival compared to those whose tumor only expressed one or none of the 2 proteins." (PMID 26214683, 2015). "However, the hypoxia-induced DNA demethylation of the TWIST1 promoter or the SW480 genome appears to be independent of TET1 and TET2, which is in line with the fact that tumor hypoxia would reduce the TET enzymatic activity." (PMID 40764968, 2025). "The report also demonstrated that Twist1 and STAT3 were crucial for the pirarubicin chemoresistance and tumor recurrence in non-muscle invasion bladder cancer, and this result could be reversed via DAB2 interactive protein." (PMID 32872659, 2020).
tumor (continued). "Of note, neither in tumour samples nor in the cell lines could we detect a correlation between S100 proteins and the other EMT-TFs, ZEB2, TWIST1 or SNAIL2." (PMID 31123345, 2019). "Moreover, another study showed that Twist1 is essential for the acquisition of CSC properties; however, cancer stemness is independent of EMT or tumor invasion, implying that EMT and stemness are regulated separately." (PMID 28649800, 2017). "We evaluated expression of TWIST1 and SLUG in tumor tissue, but not other EMT inducing TFs, therefore, we cannot exclude, that expression of other EMT TFs could be associated with presence of CTCs in peripheral blood." (PMID 26194471, 2015). "As for TWIST1, DKK3 might be useful as a cancer marker, but could not predict tumor progression, nor explain recurrence after hormonal therapy." (PMID 20976069, 2010). "The role of Twist1-induced CCL2 in angiogenesis has been demonstrated, which raises the possibility that FOXQ1 may induce angiogenesis in CRC by inducing Twist1; however, a role for FOXQ1 in inducing tumor angiogenesis and TME modification in CRC has not been evaluated." (PMID 33330033, 2020). "Although the expression of TWIST1 and SNAI2 correlated with the co-activation of Vimentin and N-cadherin and hence with the initiation of a mesenchymal differentiation program, in our tumor series they failed to correlate significantly with clinical-pathological characteristics." (PMID 22201613, 2011). "Thus, the negative correlation of TWIST1 (r = -0.54, p < 0.01), LAMB1 (r = -0.58, p < 0.001), and THY1 (r = -0.48, p < 0.01) in low tumor Hp expression groups could be a signature of poor cancer differentiation also the prognostic role of Hp in HCC cancer cell differentiation." (PMID 28158312, 2017).
cancer (823 papers, 2007 to 2026). A tumor composed of atypical neoplastic, often pleomorphic cells that invade other tissues. "While cellular expression of Twist1 has been associated with cancer invasion and metastasis, our study uncovers a novel finding: 4T1 cell-derived EVs-packaged Twist1, targeting the mPFC, plays a pivotal role as a key crucial contributor to CID." (PMID 40963917, 2025). "Studies have shown that Twist1 plays a critical role in cell migration and metastasis and high expression of Twist1 is associated with poor clinical outcomes in cancer patients." (PMID 40344465, 2025). "In the following, we provide the first direct evidence that one of the DNA methyltransferases, DNMT3A, is required for hypoxia-induced transcriptional activation of the EMT-associated gene TWIST1 in cell lines of three different cancer cell types." (PMID 40764968, 2025). "GLI, a key effector of Hedgehog signaling, has been implicated in maintaining cancer stem-like properties, while TWIST1 plays a crucial role in EMT induction and resistance to apoptosis 80,81." (PMID 40596459, 2025). "TWIST1 is listed as a transcriptional regulator at CIDR +12 h: this gene is associated with cancer metabolism and regulates the epithelial-to-mesenchymal transition." (PMID 38547106, 2024). "In the multivariable analysis for cancer detection, a positive TWIST1/Vimentin methylation were significantly linked to a heightened risk of BC." (PMID 38575639, 2024). "Increased expression of the transcription factor Twist1 is associated with metastasis and poor survival in many human cancers, including BC." (PMID 37208442, 2023). "Among the EMT-TFs, the overexpression of Twist1 is linked to poor prognosis in patients with various cancer types." (PMID 37495969, 2023). "TWIST1 is highly expressed in various cancer cells and its expression is associated with cancer cell invasion and metastasis." (PMID 38092725, 2023). "A transcriptional factor Twist1 has been associated with not only the embryonic development, cancer, and fibrotic diseases, but also the regulation of lipid and glucose metabolism." (PMID 37784111, 2023). "These cancer-promoting somatic mutations affect transcription factors such as TWIST1 (Twist-related protein 1), thereby altering the T-cell effector function and driving lymphomagenesis into proliferation." (PMID 36559182, 2022). "First, TWIST1, through induction of stemness-associated reprogramming markers, endows cancer cells with self-renewal and reprogramming capabilities to stimulate the conversion of non-CSCs to CSCs." (PMID 36474162, 2022). "SPOP promotes K63-and K48-linked ubiquitination of TWIST1, predominantly at K73, thereby suppressing cancer cell migration and invasion." (PMID 36115849, 2022). "The bHLH transcription factor TWIST1 is expressed in breast, liver, prostate, gastric, colorectal, and other types of cancers, and its expression is usually associated with invasive and metastatic phenotypes." (PMID 34809669, 2021). "The EMT-associated transcription factors Zeb1, Snail1, and Twist1 play roles in the regulation of EMT during the metastasis of cancer cells through different signaling cascades, including the Akt and ERK1/2 pathways." (PMID 33567682, 2021). "For example, TWIST1 is a recognized driver of cancer-associated myofibroblasts, and TWIST1-high myofibroblasts promote the proliferation, migration, and invasion of cancer cells." (PMID 34921160, 2021). "The consistent significance of Twist1 gene in cancer biology involves its overexpression which is linked to metastasis, therapeutic failure, recurrence, and inferior prognosis." (PMID 34234737, 2021). "Twist1 is not only involved in the development of acquired drug resistance in human cancer cells but is also associated with chemotherapy resistance when overexpressed, leading to a poorer prognosis." (PMID 33768509, 2021). "Twist1 is also implicated in playing an essential role in the expansion of cancer stem cells and resistance to chemotherapy." (PMID 33768509, 2021).
cancer (continued). "It has been reported that high expression of Twist1 is associated with aggressive cancers such as breast cancer, gastric cancer, pancreatic cancer, and liver cancer." (PMID 34408201, 2021). "Twist1 is commonly associated with angiogenesis in cancer, although the regulatory targets of Twist1 in this context have yet to be determined." (PMID 34830027, 2021). "A key regulator of cancer-associated fibroblasts, TWIST1, presented a noticeable focal gain >20%, and a regulator of angiogenesis, VEGFB (vascular endothelial growth factor B), presented a noticeable focal gain >40%." (PMID 33050525, 2020). "It has been previously demonstrated that EMT is often associated with acquisition of stemness traits in cancer cells, and that both TWIST1 and miR-145-5p control the acquisition of stem cell properties in these cells." (PMID 33227047, 2020). "Increased MYC and TWIST1 expression was associated with significantly worse disease-free survival (DFS) (p=4.3×10−10) in the pan-cancer cohort." (PMID 31933479, 2020). "Mutations that increase the levels of two proteins known as MYC and TWIST1 in cells cause many human cancers." (PMID 31933479, 2020). "Increased expression of mesenchymal markers, such as ZEB1, SNAIL, and Twist1, have been shown to induce cancer EMT and to be closely associated with the generation of cancer stem cells." (PMID 31861383, 2019). "Twist1, a key transcription factor regulating epithelial–mesenchymal transition and cancer metastasis, is highly expressed in invasive cancers in contrast to the loss of BTG2/TIS21 expression." (PMID 31138781, 2019). "TWIST1, a basic helix loop helix transcription factor, is known to associate with mesenchymal and cancer stem cell phenotypes." (PMID 30548372, 2019). "Here, we report that Twist1, a key regulator of cancer-associated fibroblasts, directly upregulates Prrx1, which, in turn, increases the expression of Tenascin-C (TNC)." (PMID 30069061, 2018). "The experiment by Zhu Zusen group proved that NRARP knockout led to attenuate cancer cell stemness which is linked with EMT by TWIST1 and ZEB1, two EMT related transcription factors that are also highly correlated with NRARP." (PMID 28207739, 2017). "Human fibroblast cell lines stably-transfected with TWIST1 acquire characteristics of activated cancer-associated fibroblasts (CAFs) and an increased ability to migrate." (PMID 29258163, 2017). "As crucial EMT inducers, Twist1 and Snail1 are up-regulated in many types of cancer and are associated with increased invasive behavior in cancer cells." (PMID 26840564, 2016). "Twist1 overexpression is associated with increased invasiveness and metastatic potential in several cancers including human glioma, neuroepithelial malignancies, hepatocellcular carcinoma, breast, esophageal, and others." (PMID 27023622, 2016). "As crucial EMT inducers, Twist1 and Snail1 are up-regulated in many types of cancer and are associated with the increased invasive behavior of cancer cells." (PMID 26840564, 2016). "Of note, STAT3 signaling is not only important for cancer cells in antagonizing apoptosis but has also been reported to be associated with cancer EMT by STAT3 transcriptional activation of EMT inducers TWIST1 and ZEB1 involved in E-cadherin repression." (PMID 27580057, 2016). "Our findings using a well-characterized cohort of 112 patients and preoperative cancer biopsies also support an association of TWIST1 expression and adverse clinicopathological features." (PMID 25528769, 2015).